IL2 (interleukin 2)
Diseases named in the same sentence as IL2 in open-access papers (continued):
Sharing a sentence is not in itself a finding about the gene and the disease.
tumor (continued). "Preclinical and clinical evidence indicates that combining cytokines with complementary mechanisms such as IL-2 with TNFα, IL-12, can produce synergistic immune activation and improved tumor control (48, 80; )?." (PMID 41568361, 2025). "In this model, serine/glycine deprivation significantly reduced tumor-reactive T cell cytotoxic activity and the expression of key T cell effector cytokines, including IL-2, TNF, and IFNγ." (PMID 40389477, 2025). "In light of this, our studies indicate that XmAb808 causes localized IL2 secretion, along with upregulation of its receptor (CD25), creating an autocrine positive feedback loop for tumor-reactive T cells." (PMID 39301613, 2025). "In parallel, groups treated with either CXCR4 inhibitor or IL-2 alone showed a marked inhibition of tumor proliferation compared to controls." (PMID 40698080, 2025). "Our preclinical studies in both anti-PD-1-sensitive and anti-PD-1-resistant mouse tumor models demonstrated that mAWT020 exhibited superior anti-tumor efficacy compared to either anti-PD-1 antibody or IL-2 alone, or their combination." (PMID 40046051, 2025). "Some investigators have demonstrated that IL-2 production by CD8+ T cells indirectly upregulates anti-apoptotic molecules on the surface of conventional CD4+Foxp3+ Tregs in the tumor microenvironment to promote tumor growth." (PMID 40553564, 2025). "Overall, the innovative IL-2 therapy we proposed solved the dilemma faced by conventional IL-2 therapy, expanding the application of IL-2 therapy in the field of tumor immunology and holding clinical translational value." (PMID 40009662, 2025). "Western blot and ELISA confirmed that US triggered IL-2 expression and secretion specifically within the tumor." (PMID 41041051, 2025). "The volume of supernatant for tumor treatments was determined based on IFN-γ levels in the culture media of primary IL-2 + anti-CD16 mAbs-treated NK cells and sNK cells." (PMID 40890122, 2025). "For instance, Astragalus polysaccharide, an active ingredient in Astragalus, activates T-cells and enhances their anti-tumor function by stimulating the secretion of immune factors such as IL-2 and IFN-γ." (PMID 40406101, 2025). "Early on, IL-2 promotes activation of effector T and NK cells, which are essential for targeting and eliminating tumor cells." (PMID 41376630, 2025). "For example, the gp100 peptide cancer vaccine, when administered alongside high-dose IL-2, has effectively stimulated tumor-reactive T cell production in the majority of patients, achieving an ORR of 42%." (PMID 39789208, 2025). "In the Renca murine renal carcinoma model, daily localized delivery of IL-2 liposomes near the tumor site suppressed tumor progression and extended survival." (PMID 40143046, 2025). "Significantly more T cells were observed in both primary tumour and liver metastasis tissues in the triple therapy group combined with IL-2 injection for 14 days (IL-2/14d) compared to all other experimental groups." (PMID 40361460, 2025). "Regarding administered (exogenous) ALT CD8+ T cells, IL-2 ALT in tumor also predominantly consisted of TEFF cells, while IL-7 ALT consisted of a mixed central/effector (TCM/TEFF) population." (PMID 40244705, 2025). "They drive NKs exhaustion and facilitate tumor immune escape by depleting activation factors like IL-2, releasing immunosuppressive molecules such as TGF-β and IL-10, and activating inhibitory receptors on NK cells, including PD-1 and TIGIT." (PMID 40008144, 2025). "Recent advances in our understanding of T-cell biology suggest that IL-2Rα/β/γ engagement by IL-2 on tumor-specific CD8 + T-cell subsets is essential for optimal CD8 + T-cell priming, “better effector” T-cell differentiation and antitumor immunity." (PMID 40410571, 2025). "A Phase I/II trial demonstrated that vaccination with DCs containing either telomerase and HLA-A2 binding peptides or tumor lysate in combination with IL-2 resulted in stable disease for 8 weeks in 48% of patients with mRCC." (PMID 39858107, 2025).
tumor (continued). "The anti-tumor effect was further enhanced when IL-2 was used to stimulate CD4+ T cells during EV production, resulting in an increased yield of CD4+ T cell-derived EVs and further strengthening the CD8+ T cell immunity." (PMID 40006624, 2025). "Accordingly, the level of mitochondrial ROS was moderately changed in Neo-2/15-stimulated BBζ, whereas markedly enhanced in IL-2-stimulated BBζ when co-cultured with tumor cells." (PMID 40025022, 2025). "Immune-related pathways, including T-cell receptor regulation of apoptosis and IL-2 signaling, were upregulated in both tumor clusters (C00, C04) as well as in cytotoxic T cell (C07) and cancer-associated fibroblasts (CAF; C12) neighborhoods." (PMID 41138165, 2025). "This has added more activation of immune effector cells, like CTLs and NK cells, in the killing of tumor cells to cytokines, especially IL-2, since such cells play a critical role in antitumor cell responses." (PMID 40309351, 2025). "Oncolytic vaccinia viruses express IL-2, IL-10, IL-12, IL-15, IL-21, IL-23, IL-24, and IL-36γ remodel the tumor microenvironment,enhance immune cell infiltration, suppress immunosuppressive elements and promot systemic antitumor immunity." (PMID 40469178, 2025). "This combination decreased tumor multiplicity, increased the amount of interleukin-2 (IL-2) in the tumor environment, activated antioxidant enzymes, and decreased histological score and tumor blood vessel area." (PMID 40179064, 2025). "By the 48-hour timepoint, IL-7–ALT T cells made up approximately 20% of all T cells in tumor, (mean 18.8%, SD ±4.3%, n = 5), while the fraction of T cells that consisted of IL-2 ALT in tumors was approximately 1% (mean 1.7%, SD ±1.5%, n = 4)." (PMID 40244705, 2025). "Leveraging thisin vivomodel of TCE treatment failure, we discovered that co-treatment with TCE and a CD25-biased Interleukin-2 (IL2) rescues anti-tumor activity." (PMID 41573936, 2025). "A recent study showed that IL-2 promoted the expansion and intratumoral accretion of tumor-infiltrating DCs in PDAC." (PMID 40427186, 2025). "The limitations of conventional IL-2 therapy for tumor treatment include its limited capability to induce durable immune responses due to its short half-life." (PMID 40009662, 2025). "Following the euthanasia of the mice, the analysis of tumor cells revealed decreased IL-2-related toxicity and increased tumor control." (PMID 40699676, 2025). "The TIL culture method was based solely on tumor tissue with low IL-2 supplementation to minimize artificial alterations." (PMID 41383591, 2025). "Mice immunized with 100 μg CpDV-IL2-MS had equivalent IFN-γ secretion, tumor cell cytotoxicity, tumor growth rates and survival compared to mice treated with CpMS+IL-2." (PMID 41012179, 2025). "Splenocytes of mice were harvested at 12 days post initial injection of oncolytic Ad and co-cultured with irradiated B16-F10 tumor cells for 3 days in the presence of recombinant mouse IL-2." (PMID 40335925, 2025). "While five TRuC T-cell products efficiently killed all three tumor cell lines, the Track 2 C10 vLvH TRuC T cells secreted markedly higher levels of both IFN-γ and IL-2 in response to tumor culture compared with all other candidates." (PMID 40519930, 2025). "Robust effector function ensures effective immune defence against infections and tumours, even in ageing organisms where IL-2 production is often impaired." (PMID 41194200, 2025). "The study found that T-cell receptor-independent activation of γδ T cells with cytokines, including IL-2, IL-12, and IL-18, increased their anti-tumor potential." (PMID 40584290, 2025). "Here, we determined the levels of three relevant cytokines involved in tumor progression: (a) IL-2, (b) IL-6, and (c) TNF-α." (PMID 41155954, 2025).
tumor (continued). "Only the triple therapy with prolonged IL-2 demonstrated significant improvement in overall survival, highlighting the rapid progression of the tumour model was challenging our ability to fully explore the real potential of triple therapy." (PMID 40361460, 2025). "In CRC mice treated with anti-CTLA-4 and Lactobacillus acidophilus lysates, tumor reduction was associated with increased IL-2, IFN-γ, and CD8+ T cell infiltration, with Bifidobacterium upregulating tumor-specific CD8+ T cells and IFN-γ secretion." (PMID 39996827, 2025). "These CD4+ T cells were ex vivo expanded with the treatment of Δ35 mM NaCl, anti-CD3/CD28, IL-2 and IL-7 along with heat-killed tumor cells." (PMID 40563574, 2025). "For instance, sulfated fucoidan SHPPB2 from Sargassum fusiforme stimulates splenocyte proliferation and induces anti-inflammatory cytokine production (IL-2, IL-4, IL-10) in tumor-bearing rats." (PMID 41149588, 2025). "The solution containing both TILs and tumour cells was incubated with Interleukin (IL)-2 (a T-cell growth factor) for several weeks to expand the TIL population while the tumour population was depleted." (PMID 39959909, 2025). "Ultrasound irradiation enabled the therapeutic protein (IL-2 or sPD-1) to be spatiotemporally switched-on within the tumor region." (PMID 41041051, 2025). "IHC revealed significantly enhanced staining for IL2 protein in MC38‐luciferase tumor tissue from Gpr4−/− mice compared to WT mice." (PMID 40397803, 2025). "Antitumor efficacy evaluations demonstrated that these immunoliposomes maintained the potent therapeutic effect of IL-2 while reducing systemic toxicity across multiple tumor models." (PMID 40557148, 2025). "Cytokine transfection is a technique that utilizes gene editing to introduce or amplify specific cytokines, such as IL-15 and IL-2, to enhance NK cell survival, proliferation, and function, thereby augmenting their anti-tumor effects." (PMID 40391220, 2025). "For example, MSCs engineered to deliver IL-2 mutein dimer to tumor-infiltrating T cells exhibit capacity to reinvigorate exhausted CD8+ T cells, making it a more potent antitumor therapeutic agent." (PMID 39971901, 2025). "IL-2, a key growth factor for tumor-infiltrating lymphocytes, suggests that CD8+CD28+PD1− T cells possess superior proliferative potential." (PMID 40136325, 2025). "Allen and colleagues engineered CAR T cells with a synthetic Notch receptor which secrets IL-2 upon tumor recognition." (PMID 40636106, 2025). "Activation of NK cells with IL-2 has been shown to increase their ability to lyse tumor cells by enhancing perforin binding to the target cell membrane." (PMID 40255394, 2025). "The data demonstrated that both CAR-T cell groups with IL-2 injection exhibited anti-tumor effects compared to the NT+IL-2 group, with the anti-HER2-13 CAR-T group showing a statistically significantly greater reduction in tumor weight (p = 0.0322)." (PMID 41179290, 2025). "Related studies also indicate that Bempegaldesleukin, an IL-2 pathway agonist, significantly enhances the anti-tumor efficacy of radiotherapy through a T cell–dependent mechanism." (PMID 41376630, 2025). "Hyperthermia also augments cytotoxic lymphocyte (CTL) and NK cell activity—facilitated by NKG2D receptor clustering and HSP70 interaction—while boosting IL-2 production, T-cell proliferation, and tumor-directed cytotoxicity." (PMID 41375025, 2025). "IL-2 is critical to the survival, growth, and activation of T-cells and NK cells; it showed clear anti-tumor effects." (PMID 40670434, 2025). "As IL-2R is found on a variety of immune effector and regulatory cell types, including effector T cells, regulatory T cells (Tregs), and NK cells, signaling through IL-2 can have pleiotropic effects upon anti-tumor immunity." (PMID 40760075, 2025). "lactis BX-245, which enhanced Akkermansia levels within the tumor microenvironment, strengthened the intestinal barrier, and elevated systemic immune mediators such as IL-2 and IFN-γ." (PMID 41305617, 2025).
tumor (continued). "This process allows BCG to act as a pathogen-associated molecular pattern (PAMP), triggering APC activation, IL-2 production, and an immune response against tumor cells." (PMID 40699676, 2025). "For example, pairing polyethylene glycol-coated liposomal doxorubicin (Doxil) with liposomal IL-2 for treating M109 lung adenocarcinoma in mice produced prolonged tumor-free survival in nearly all cases, markedly outperforming chemotherapy alone." (PMID 40143046, 2025). "Currently, multiple IL-2-based products are under clinical and pre-clinical investigation, requiring evaluation of their effects to reprogram dysfunctional state of anti-tumor CD8+ T cells." (PMID 41268548, 2025). "This interaction triggers T-cell activation, cytokine production (e.g., IFN-γ, IL-2), and release of cytotoxic granules (perforin, granzyme B) to mediate tumor cell lysis." (PMID 40940995, 2025). "Lymphocytes, particularly tumor‐infiltrating CD8+ T cells supported by CD4+ T cells (via IL‐2 and interferon‐gamma), are essential for anti‐tumor immunity." (PMID 41307215, 2025). "Another phase I trial by the DFCI explores the efficacy of CIML NK cells in patients with renal cell carcinoma and urothelial carcinoma, assessing IL-2’s role in augmenting NK cell-mediated tumor clearance." (PMID 40498022, 2025). "As a result, various IL-2 immunocytokines, which consist of IL-2 fused to antibodies targeting different tumor or TME antigens, have been developed and evaluated in tumor mouse models, yielding encouraging results." (PMID 39852848, 2025). "Trispecific antibodies that include IL-15 have demonstrated the ability to enhance natural killer and T-cell proliferation, while tumor-localized IL-2 delivery helps activate immune cells directly at the tumor site with minimal systemic side effects." (PMID 39982231, 2025). "A fusion construct of IFN-α and IL-2 significantly inhibited tumor growth in a mouse model by inducing apoptosis of tumor cells, and enhancing the anti-tumor immune response of T cells and NK cells." (PMID 41030448, 2025). "Cytokine therapy has emerged to increase anti-tumor immunity using lymphocyte activators such as IL-2." (PMID 40670434, 2025). "The combination of vaccine and ICI also promoted IFNγ, IL2, and granzyme B production in the tumor microenvironment, suggesting enhanced activation of antigen-specific T cells." (PMID 41012179, 2025). "Stimulated NK cells (IL-2) and treated tumor cells were co-cultivated with a Target: Effector (T: E) ratio of 1:1." (PMID 40883442, 2025). "In this report, we constructed novel oncolytic rVACV strains to explore the anti-tumor effectiveness of TAAs-derived peptides and/or IL2 expressed by these virus strains in 4T1 tumor-bearing immunocompetent BALB/c mice." (PMID 41050655, 2025). "In 1982, Steven Rosenberg, widely considered as the father of ACT, first isolated TILs from a murine tumor model and expanded them in vitro in the presence of IL-2." (PMID 40458394, 2025). "Collectively, these analyses showed that ICIs plus IL-2/JES6 treatment leads to effective anti-cancer activity through potent expansion of tumor-specific CD8+ T cells that exhibit effector phenotype." (PMID 40789741, 2025). "The in vitro potency of CD70 TRuC T cells was assessed by measuring their tumor lytic activity and inflammatory IL-2 and interferon-gamma (IFN-γ) cytokine release response to CD70+ tumors." (PMID 40519930, 2025). "It is known that IL-2 is involved in the upregulation of the anti-tumor immune response; however, a direct action of IL-2 on RCC cells has not yet been demonstrated." (PMID 41150778, 2025). "The concentrations of immune‐promoting Th1 cytokines (IFN‐γ, TNF‐α, and IL‐2) as well as proinflammatory signal (IL‐6) determined in culture supernatants and tumor tissues were evidently higher in N@VP + 2 Gy group." (PMID 40231790, 2025).
tumor (continued). "It has been reported that the exhausted T cells in the tumor microenvironment have a reduced capacity to generate cytokines like IL2 and lose their effector activities to regulate tumor development." (PMID 40407494, 2025). "CD4+CD25+ Tregs competitively suppress the immune response to tumor cells by binding the IL-2 high affinity receptor to IL-2, and IL-2 is one of the cytokines of the primary stimulatory production of Teff." (PMID 40216744, 2025). "Membrane-bound HSP70 (mHSP70) released from tumor cells under the influence of interleukin-2 (IL-2) has been shown to activate natural killer (NK) cells." (PMID 39911383, 2025). "The results showed that APS not only suppressed tumour growth, but also significantly increased the thymus and spleen indices and enhanced the production of serum cytokines IL-2, IL-6, and TNF-α." (PMID 40649307, 2025). "Novel CAR-T armed with a synNotch receptor that upregulated IL-2 expression when in contact with specific antigens, reported greater tumor-infiltration and better efficacy." (PMID 40584631, 2025). "PEGylated liposomal IL-2 formulations, for example, have shown reduced accumulation in the kidneys and liver while increasing localization in tumor tissues." (PMID 40143046, 2025). "The activated T cells would in turn upregulate CD25, resulting in selective activation of tumor antigen-specific T cells by the CD25-biased IL-2/JES6." (PMID 40789741, 2025). "IL-2 enhances the natural ability of the immune system to kill tumours by increasing the tumouricidal activity of the cytotoxicity of CD8+ T cells and natural killer (NK) cells." (PMID 40075668, 2025). "The fourth generation of CAR-T cells, known as “TRUCK” cells, have enhanced the secretion of cytokines, such as IL-12 and IL-2, which play a crucial role in regulating the tumor immune microenvironment." (PMID 40370457, 2025). "Assessment indicators included tumour weight and inhibition rate, spleen and thymus indices, serum cytokine levels (IL-2, IL-12, TNF-α, IL-10), as well as the phagocytic rate and phagocytic index of peritoneal macrophages." (PMID 40649307, 2025). "Pro-inflammatory cytokines, including IL-2, TNFα, IL-1β, and IL-6, contribute to shaping a tumor-promoting microenvironment by sustaining inflammation and facilitating cancer cell survival and dissemination." (PMID 41614846, 2025). "For instance, cytokines like interferon-alpha (IFN-α) and interleukin-2 (IL-2) have demonstrated efficacy in enhancing anti-tumor immune responses by activating T cells, NK cells, and macrophages." (PMID 40731885, 2025). "This slow-release system increased spleen cell cytotoxicity and recruited tumor-infiltrating lymphocytes, including Lyt-2+ and L3T4+ cells, into the tumor, indicating that liposomal IL-2 stimulates a strong localized immune response." (PMID 40143046, 2025). "A significant increase in CD8+ cells and IL-2 in the peripheral blood of mice with tumours was detected by flow cytometry using CD3+ monoclonal antibody." (PMID 40077614, 2025). "The importance to selectively deliver IL-2 to the site of disease using the L19 antibody has been previously demonstrated in multiple murine tumor models." (PMID 39773310, 2025). "In concordance with this, the deletion of NR4A1 in T cells results in increased T cell effector function and enhanced tumor suppression through the increased production of IL-2 and IFN-γ and decreased PD-1 expression." (PMID 40508074, 2025). "Loaded with immune modulators such as TGF-β and IL-2 and Promote immune cell infiltration at tumor sites." (PMID 40391220, 2025). "TILs are first either isolated from a single-cell suspension after the enzymatic digestion of the tumor tissue or directly cultured from small fragments of fresh tumor tissue followed by in vitro expansion with a high dose of IL-2." (PMID 40145091, 2025). "Mock T cells, CT103a, and nanoCAR-T-cell types were activated using CD3/CD28 beads and IL-2 for 8 days before being co-cultured with tumor cells." (PMID 41439964, 2025).